EGFR (epidermal growth factor receptor)
Diseases named in the same sentence as EGFR in open-access papers (continued):
Sharing a sentence is not in itself a finding about the gene and the disease.
cervical carcinoma (continued). "Interestingly, our previous work dealing with the silencing activity of B-ASOs achieved by the antisense approach towards the EGFR mRNA reached a maximum of 83–95% with the double negative boron cluster [(−2) DDB] in HeLa cervical cancer cells." (PMID 36293047, 2022). "In addition, miR-125a-5p could inhibit the progression of cervical cancer by down-regulating the activity of GALNT7 and the EGFR/PI3K/AKT signaling pathway." (PMID 36313765, 2022). "It is of interest to note that, by binding and activating EGFR, both AREG and transforming growth factor α (TGFα) induce the dephosphorylation of LATS1, MOB1 and YAP in the Hippo signaling pathway, thus activating YAP that drives the proliferation and migration of cervical cancer cells." (PMID 33467099, 2021). "EGFR has been considered to be a receptor involved in cervical cancer progression, however, clinical trials are still not conclusive as to whether blocking EGFR is effective enough for justifying its use in the clinical setting." (PMID 33886813, 2021). "However, the upregulation of LPCAT2 (P = 0.0239), the same enzyme that positively correlates with the expression of EGFR, showed negative prognostic value for cervical cancer patients, as well as cPLA2 (P = 0.0052)." (PMID 33392068, 2020). "Although there are some targeted drugs that may be effective for cervical cancer, such as PARP inhibitors (for BRCA1 or BRCA2 mutations patients), EGFR tyrosine kinase inhibitors (for EGFR mutations patients), gene detection is still not widely used in China." (PMID 32265980, 2020). "For instance, Cetuximab, a chimeric immunoglobulin G2 monoclonal antibody that binds specifically to EGFR and competitively inhibits the binding of EGF and other ligands, has been developed to be used in patients with different cancers with high expression of EGFR including cervical cancers." (PMID 31470515, 2019). "While epidermal growth factor receptor (EGFR) tyrosine kinase inhibitors (TKIs) are widely used for the treatment of diverse types of cancer, whether EGFR-TKIs are effective against chemoresistant CSCs in cervical cancer is largely unknown." (PMID 31772161, 2019). "However, the role of PAR-mediated EGFR transactivation in cervical cancer cells has not been previously investigated." (PMID 30093972, 2018). "Furthermore, EGFR, PAR2 and COX2 have independent prognostic value in cervical cancer patients." (PMID 30093972, 2018). "In this study, we examined the expression of receptor tyrosine kinases, EGFR, HER2 and c-MET, in cervical adenocarcinomas to determine whether they are useful as prognostic factors and therapeutic targets of cervical cancers, with focus on the importance of co-expression of multiple RTKs." (PMID 28859123, 2017). "Here, we explored the cytotoxic efficacy on ten cervical cancer cell lines of activated allogeneic NK cells from two sources, i.e., peripheral blood (PBNK) with and without cetuximab (CET), a tumor-specific monoclonal antibody directed against EGFR, or derived from umbilical cord blood (UCB-NK)." (PMID 27783105, 2017). "Thus, we identified a new pathway employing miR-2861, EGFR, AKT2, and CCND1 that may mediate HPV16 E6 induced initiation and progression of cervical cancer." (PMID 27364926, 2016). "Since AREG is a member of the family of the EGF-like ligands and we have shown that the EGFR pathway interacts with the Hippo pathway to regulate cervical cancer cell growth, we infer that AREG may also be involved in the regulation of cervical cancer cell proliferation." (PMID 26417066, 2015). "Therefore, anti-EGFR/HGNs will be selectively uptaken by cervical cancer cells and induce their apoptosis, as a result reducing nonspecific injury to normal cells when combined with radiotherapy." (PMID 25995714, 2015).
cervical carcinoma (continued). "However, the clinical utility of EGFR expression as a biomarker for prognosis or for treatment of cervical cancer is not defined, as normal cervical epithelium also expresses EGFR at various levels, and this expression is not correlated with the HPV type." (PMID 25070070, 2014). "In contrast, treatment with matuzumab for 24 h failed to induce EGFR down-regulation in both cell lines, demonstrating that this event is independent of the cell type analyzed ( Caski is a cervical carcinoma and A431 is a vulvar carcinoma)." (PMID 22185378, 2011). "As this pattern of EGFR gene amplification has not been previously documented with FISH in cervical carcinomas, further studies are required to confirm our results and elucidate the relationship between EGFR gene amplification and tumour sensitivity to radiation." (PMID 21730982, 2011). "Finally, our data indicate that cervical cancer, the hallmark of which is HPV infection, is an EGFR-sensitive disease regardless of ligand-dependent or ligand-independent stimulation." (PMID 21822357, 2011). "However, EGF-elicited signal transduction is not the only mechanism mediated by anti-EGFR MAbs, since these molecules can also induce ADCC and, in primary cervical cancer cell lines obtained from cervical biopsies, ADCC induction was dependent on EGFR expression." (PMID 22185378, 2011). "However, EGFR expression did not correlate with cPLA2 expression levels in cervical cancer samples." (PMID 33392068, 2020). "Regarding G2/M process modulation by E2, in human cervical cancer cells, non-classical membrane estrogen receptors G protein-coupled receptor (GPER) activation induced G2/M cell cycle arrest via EGFR/ERK1/2 signals." (PMID 35197928, 2022). "Other proteins orchestrating EGFR signaling, including ERK, pAKT and PTEN, were not related to survival in patients with cervical cancer." (PMID 34830902, 2021). "In Figure, two TIR fluorescence images are depicted for HeLa cervix carcinoma cells stably transfected with Grb2-YFP, and transiently transfected with EGFR-CFP without further stimulation." (PMID 30717378, 2019). "Observations such as these merit further investigation of the potential of nonsteroidal anti-inflammatory drugs, EGFR inhibitors and PAR2 antagonists as adjuvants to chemotherapy regimens for patients with cervical cancer." (PMID 30093972, 2018). "EGFR is not upregulated e.g. in human breast epithelial MCF10A, cervix carcinoma HeLa or human keratinocyte HaCat cells upon stable flotillin-1 knockdown (our unpublished findings)." (PMID 24304721, 2013). "So far, the expression of EGFR and HER2 has only been determined in primary cervical cancers, and we have not found published data regarding the receptor status in corresponding metastatic lesions." (PMID 18700025, 2008). "Based on the assumption that the MAPK pathway can induce c-fos, and on the fact that the overexpression of the epidermal growth factor receptor (EGFR) has been reported in cervical cancer cells, we suggest that the modulation of c-fos is not only dependent on GPER1 but also on EGFR." (PMID 36231664, 2022). "However, cervical cancer cell lines were sensitive in varying degrees to PBNK-induced cell lysis, independent of their EGFR expression levels, with consistently and significantly higher cytotoxicity rates when coated with CET (P = 0.002)." (PMID 27783105, 2017).
cervical carcinoma (continued). "In some, but not all, cervical cancer cell lines a benefit was seen in combining cetuximab with an anti-TKI, an anti-MEK1/2, or even with trastuzumab suggesting that targeting EGFR alone may not be enough." (PMID 22091418, 2011).
small cell lung carcinoma (303 papers, 1998 to 2026). Small cell lung cancer (SCLC) is a highly aggressive malignant neoplasm, accounting for 10-15% of lung cancer cases, characterized byrapid growth, and early metastasis. "Overexpression of m5C methyltransferase, NSUN2 has been found to cause resistance of small-cell lung cancer to the epidermal growth factor receptor (EGFR) inhibitor, gefitinib." (PMID 40351534, 2025). "Although limited by the quantity and quality of biopsy specimens, previous studies suggested that EGFR mutations were detected in both adenocarcinoma and small cell lung cancer components in three combined SCLCs." (PMID 37436674, 2024). "For example, this study only preliminarily demonstrates the changes in PD-L1 expression levels in sEVs secreted by non-small-cell lung cancer cells under EGFR mutation and TKI treatment conditions, as well as the potential underlying molecular mechanisms." (PMID 39062533, 2024). "One case was additionally excluded diagnosed as small cell lung cancer on tissue biopsy which however detected to have EGFR mutation (exon 19 deletion) on liquid biopsy testing and then confirmed on tissue biopsy." (PMID 39066920, 2024). "NCI-H441is a KRAS-dependent lung adenocarcinoma cancer cell line, and NCI-H1975 is a non–small cell lung cancer cell line harboring EGFR L858R/T790M activating mutations." (PMID 37824212, 2023). "Despite some patients maintaining the targetable mutation, EGFR-TKIs seem to have little benefit in small cell lung cancer." (PMID 37175833, 2023). "Up to 15% of EGFR-mutated NSCLC treated with osimertinib transforms into small cell lung cancer (SCLC) or squamous cell carcinoma." (PMID 38107063, 2023). "Univariate analyses revealed that old age, male sex, history of smoking and alcohol drinking, synchronous cancer, small cell lung cancer, late-stage cancer, and undetected EGFR were associated with poor prognosis." (PMID 36233811, 2022). "The histologic conversion from EGFR-mutated NSCLC into small cell lung cancer (SCLC) has been recorded in 14% of patients progressing to first-line osimertinib and in 4–15% of patients experiencing disease progression in the second-line setting." (PMID 35805940, 2022). "During or after treatment with EGFR TKIs, a subset of individuals (i.e., 5–10%) with NSCLC and EGFR mutations develops histologic transformation of adenocarcinoma into small-cell lung cancer (SCLC)." (PMID 35209919, 2022). "In advanced NSCLC, TKI-resistant RB1-inactivated/EGFR-mutated adenocarcinoma clones have been found to transdifferentiate into small-cell lung cancer (SCLC) and become more responsive to chemotherapy." (PMID 34750392, 2021). "One hundred and thirty-three patients with small cell lung cancer or NSCLC that was treated with targeted therapy against an EGFR mutation or ALK translocations were excluded from the analysis, leaving 667 patients." (PMID 34518623, 2021). "Loss of EGFR p.T790M mutation was observed in nine patients, including all patients with a transformation to small-cell lung cancer." (PMID 33138052, 2020). "The heuristic steps in these FFTs were similar for most patients except for one who had small cell lung cancer transformation, which has been previously associated with prolonged EGFR TKI treatment." (PMID 32560187, 2020). "Several mechanisms were reported for the acquired resistance to osimertinib in EGFR-T790M mutated NSCLC patients, including EGFR-C797S mutation, bypass signal activation, and transformation to small cell lung cancer." (PMID 30875919, 2019). "Several acquired resistance mechanisms to initial EGFR-TKIs are known, including gatekeeper mutations such as EGFR-T790M, activation of bypass signaling, epithelial mesenchymal transition and transformation to small-cell lung cancer." (PMID 30875919, 2019). "A previous study has reported that repeated bioptic sampling from patients with EGFR mutation revealed histological transformation from adenocarcinoma to small cell lung cancer." (PMID 30404198, 2018).
small cell lung carcinoma (continued). "Acquired resistance to initial EGFR-TKIs is caused by various mechanisms, such as gatekeeper mutations like the EGFR-T790M second site mutation, activation of bypass signaling, and transformation to small-cell lung cancer." (PMID 30537950, 2018). "The transformation from lung adenocarcinomas to small-cell lung cancer was marked by loss of the RB gene, decreased EGFR expression, and increased neuroendocrine marker expression —all typical of small cell lung cancers." (PMID 28431544, 2017). "As well as this mechanism, c-MET amplification (5– 10%), HER2 amplification (12%), PIK3CA mutations (5%), BRAF mutations (1%), small-cell lung cancer histological transformation (3–14%) and so on are also associated with acquired resistance to EGFR-TKIs." (PMID 27409677, 2016). "Case 3 was an 82-year-old Japanese male diagnosed with hyponatremia due to inappropriate secretion of antidiuretic hormone and stage IIIB small cell lung carcinoma (SCLC) who had the EGFR mutation, L747S." (PMID 24396447, 2014). "EGFR mutations in squamous cell carcinoma and small-cell lung cancer (SCLC) are very rare and are usually found in less than 3% of cases." (PMID 24212826, 2011). "EGFR mutations are rarely found in squamous cell carcinomas of the lung, small cell lung cancer or other epithelial malignancies." (PMID 21165163, 2010). "Indeed, it was shown previously that resistance to entinostat in small cell lung cancer was associated with increased basal expression of EGFR." (PMID 39864337, 2025). "We observed various recurrent genomic alterations that may contribute to the development of small cell lung cancer in the setting of targeted therapy for EGFR mutations." (PMID 41149474, 2025). "In addition, up to 15% of EGFR-mutated patients have the risk of small-cell lung cancer transformation on progression." (PMID 38107063, 2023). "Currently recruiting EGFR mutation non-small-cell lung cancer trials." (PMID 36212398, 2022). "Therefore, our study aimed to detail and catalog the longitudinal sequencing profiles of nine EGFR-mutated patients who had pathology-confirmed small cell lung cancer transformation, as well as identify any biomarker patterns associated with improved survival." (PMID 35268520, 2022). "Using both experimental systems and patient samples, secondary/gatekeeper mutations in EGFR (T790M), c-Met amplifications, PI3K mutations, and the acquisition of mesenchymal and small-cell lung cancer features have been identified and validated as molecular determinants of EGFR TKi resistance." (PMID 34254585, 2021). "Finally, small-cell lung cancer transformation was seen in two cases of rociletinib resistance and one osimertinib-resistant patient; the T790M was lost while the original EGFR mutation was maintained in the small cell transformed cancer in each case." (PMID 28149837, 2016). "EGFR L861Q mutation was detected in both small-cell lung cancer and adenocarcinoma components." (PMID 24195468, 2013). "All patients were treated with EGFR-TKIs and eventually underwent transformation into small cell lung cancer, with a median survival of approximately 6 to 9 months after transformation." (PMID 40248195, 2025). "Small-cell lung cancer (SCLC) transformation is one of the major mechanisms of resistance to Epidermal Growth Factor Receptor tyrosine kinase inhibitors (EGFR-TKIs)." (PMID 40437627, 2025). "The current consensus is that small-cell lung cancer is transferred from adenocarcinoma following treatment with EGFR tyrosine kinase inhibitors." (PMID 38807858, 2024). "In the case of the lung, as many as 14% of non-small cell lung cancers acquire resistance to EGFR inhibitors by adopting a small cell lung cancer (SCLC) neuroendocrine-like phenotype." (PMID 37832945, 2024).
small cell lung carcinoma (continued). "This research reports a case of histological transformation from non-small cell lung cancer (NSCLC) to transformed small cell lung cancer (T-SCLC) in a patient undergoing EGFR-tyrosine kinase inhibitors (TKIs)." (PMID 39386753, 2024). "Small cell lung cancer transformation is a rare (<5%) acquired resistance to previous EGFR-TKI treatment." (PMID 37854677, 2023). "Some studies report a transformation from EGFR positive adenocarcinoma to small cell lung cancer (SCLC) at a rate of up to 10%." (PMID 37124513, 2023). "A study indicated that EGFR TKIs blocked Akt and Ets-1 activity and thus evoked gefitinib resistance in non–small-cell lung cancer cells." (PMID 37433225, 2023). "Small-cell lung cancer (SCLC) transformation from EGFR mutant adenocarcinoma is a rare entity that is considered to be a new phenotype of SCLC." (PMID 36975478, 2023). "Histologic transformation to small cell lung cancer (SCLC) is a widely known resistance mechanism to epidermal growth factor receptor (EGFR) targeted therapy in Non-Small Cell Lung Cancer (NSCLC) occurring in 3-15% of EGFR aberrated NSCLC20." (PMID 37231247, 2023). "Histologic transformation to small cell lung cancer (SCLC) occurs in 3–14% of NSCLC patients treated with EGFR TKIs." (PMID 36765587, 2023). "All patients received at least one line of EGFR TKI therapies prior to small cell lung cancer transformation, including erlotinib, afatinib, and osimertinib." (PMID 35268520, 2022). "Histopathological transformation to small cell lung cancer (SCLC) from NSCLC has been reported as a mechanism of acquired resistance to EGFR-TKIs in 3–15% of patients." (PMID 35840984, 2022). "The results revealed that the combination of crizotinib and EGFR inhibitor inhibits the emergence of EGFR-inhibitor-tolerant clones in non-small-cell lung carcinoma cells." (PMID 36233210, 2022). "Effects of mutant KRAS or EGFR expression on phenotype and neuroendocrine markers in small cell lung cancer cells." (PMID 34121659, 2021). "Chelidonine inhibited non-small cell lung cancer growth via regulating epidermal growth factor receptor/AMP-activated protein kinase (EGFR/AMPK) signaling pathways in vivo and in vitro." (PMID 33562110, 2021). "One (17%) patient showed EGFR exon 20 insertion and the last one (17%) incurred into small cell lung cancer transformation." (PMID 34771566, 2021). "Clinical and experimental observations have recently demonstrated that EGFR-mutant tumors transform into SCLC (small cell lung carcinoma) after EGFR tyrosine kinase inhibitor treatment." (PMID 33806395, 2021). "Comparatively, in EGFR 19del cohort, there was one each case had small-cell lung cancer transformation and squamous transformation from adenocarcinoma." (PMID 34774017, 2021). "Several mechanisms underlying acquired resistance to EGFR TKIs have been identified, including the acquisition of EGFR T790M mutation, c-MET amplification, PIK3CA mutations, and phenotypic transformation into small cell lung cancer." (PMID 33585221, 2020). "Small cell lung cancer transformation has been reported as an alternative mechanism of resistance to first-generation EGFR TKI in 3–14% of EGFR TKI-treated patients." (PMID 32397977, 2020). "EGFR TKI-small cell lung cancer transformation was suspected, and the patient immediately started carboplatin/etoposide chemotherapy alongside osimertinib." (PMID 32560187, 2020).